BRD4 (bromodomain containing 4)
Diseases named in the same sentence as BRD4 in open-access papers (continued):
Sharing a sentence is not in itself a finding about the gene and the disease.
cancer (continued). "In this study, we discovered that BRD4 is hyperphosphorylated specifically during mitosis in both established cancer cell lines as well as normal HDFs." (PMID 32575711, 2020). "In several human cancer models BRD4 was shown to interact with the transcription factors YAP and TAZ, thereby controlling the genome-wide association of BRD4 to chromatin and expression of tumor growth-regulating genes." (PMID 32046099, 2020). "Taking together, these results suggest that BRD4 inhibition suppresses tumor growth not only through direct inhibition of cancer cell growth, but also through blockade of the interaction between cancer cells with their supporting microenvironment." (PMID 32286255, 2020). "In contrast to BET-competitive inhibition, targeted degradation of BRD4 using the optimized degrader molecule dBET6 led to a global breakdown of transcription, therefore having more rapid and dramatic consequences in cancer cells." (PMID 33371192, 2020). "The role of BRD4 in proliferation of cancer cells has been exploited in recent years with several small molecule inhibitors entering clinical trials." (PMID 33396954, 2020). "The BET family proteins, including BRD4, have received great interest because of their therapeutic potential for treating inflammatory fibrotic diseases, including cancer and neurological and metabolic disorders." (PMID 33290278, 2020). "In cancer cells, BRD4 is disproportionately enriched at certain key oncogenic genes, such as c-MYC, and selectively upregulates their expression to drive cellular proliferation." (PMID 32575711, 2020). "The development and optimization of BRD4 small-molecule inhibitors as novel cancer therapeutics are currently a major focus of cancer research." (PMID 32978368, 2020). "BRD4 inhibitors have been tested in a number of preclinical cancer studies, showing promising anticancer outcomes." (PMID 32371868, 2020). "Alterations in regulation of activities from BET protein, especially BRD4, have been greatly allied with cancer and inflammatory diseases." (PMID 35746919, 2020). "In cancer development, BRD4 was a stimulator for the expression of cell proliferation related genes, such as c-Myc, CyclinD1 and CDK4, as well as cell migration related genes, such as MMP-2 and MMP-9." (PMID 32640974, 2020). "The potential of BRD-4 as a biomarker and regulator for various diseases including fibrosis and cancer is promising." (PMID 33796822, 2020). "Combined use of JQ1 and/or PI3K can inhibit BRD4, further inhibit the deacetylation of BRD4, improve the acetylation level of MDSCs, reduce the infiltration of MDSCs, and inhibit the tumor growth in mouse cancer model." (PMID 33027968, 2020). "The cancer models data demonstrate that simultaneous disruption of the acetyllysine binding function of BRD4 and kinase activities of PI3K and CDK4/6 improves efficacy." (PMID 32694708, 2020). "Remarkably, BRD4 inhibition seems to specifically affect the transcription of cancer-promoting genes." (PMID 32899586, 2020). "We then used JQ1, a BRD4 inhibitor, to disrupt the activity of SEs, which has been proven effective in a variety of cancers 23-26." (PMID 32802179, 2020). "The most comprehensively characterized transcription factor is nuclear factor-κB (NF-κB), which is regulated by BRD4 via binding to the acetylated lysine-310 residue of its RelA subunit in cancer cells." (PMID 33574760, 2020). "Consistently, our combined analyses of the RNA-Seq and H3K27ac ChIP-seq data for MMP2 showed varied degrees of MMP2 expression among several types of cancer cell lines, despite the equally high expression of BRD4 among them." (PMID 32499570, 2020). "BRD4 is overexpressed in multiple types of human cancers, emerges as a promising therapeutic oncotarget." (PMID 32163373, 2020). "BRD4 inhibitors have shown promising activity against multiple cancers in pre-clinical studies, and at present there are five BRD4 inhibitors in phase I/II clinical trials." (PMID 31901895, 2020).
cancer (continued). "BRD4 is reported to be upregulated in other oncogenic signaling and cancer stem cell (CSC) signaling such as Hh pathways Gli‐1 and Jagged1/Notch1." (PMID 32175692, 2020). "Although blocking BRD4 interaction with acetylated histones using BETis has been pursued in cancer clinical trials, many cancers have been found to acquire resistance to BETis." (PMID 32575711, 2020). "BRD4 is a chromatin reader protein that acts as a transcriptional coactivator involved in physiological hematopoiesis and is recruited in cancer development." (PMID 32899586, 2020). "Bromodomain containing 4 (BRD4) is a crucial epigenetic protein, and it has been reported to elevate the levels of oncogenic proteins and accelerate the progression of cancers." (PMID 32782441, 2020). "Many small‐molecule inhibitors, such as JQ1, were developed to disrupt protein–protein interactions between BRD4 and acetyl lysine, which effectively block cell proliferation and cytokine production in acute inflammation in cancers." (PMID 31908141, 2020). "Though blocking BRD4′s interaction with acetylated histones using BETis has been pursued as the principal treatment strategy for BRD4-driven cancers, BETi resistance has emerged in the vast majority of cancers." (PMID 32575711, 2020). "Consistent with the frequent BRD4 transcriptional upregulation in carcinomas, BRD4 overexpression in the progression of GISTs likely occurs in part because the transcriptional machinery follows altered signalling stimuli." (PMID 31957165, 2020). "BRD-4 is shown to stabilize and help the growth of carcinoma and inhibition of BRD-4 using gene silencing or inhibitors, which significantly reduced tumor progression." (PMID 33796822, 2020). "The first compound reported to target SEs is ‘JQ1’, designed to specifically inhibit Bromodomain and Extraterminal (BET) superfamily member BRD4 that highly occupies SEs in cancer cells." (PMID 31724731, 2019). "In this study, BRD4 expression in cancer and its influence on the prognosis of cancer patients were analyzed using data from public databases." (PMID 30988278, 2019). "Since the anticancer effect of JQ1 is mainly derived from its inhibition of BRD4, we first explored the role of BRD4 in cancer." (PMID 30988278, 2019). "This is possible because of super-enhancers, which are central for cancer cells survival and are specifically dependent on BRD4 activity." (PMID 30841549, 2019). "Recently, several laboratories reported a BD1-dependent role of BRD4 in the DNA damage response pathway, raising additional concerns regarding BRD4 function involved in the viabilities of normal and cancer cells." (PMID 31586052, 2019). "Next, we analyzed the relationship between BRD4 expression and prognosis in cancer patients included in the TCGA database." (PMID 30988278, 2019). "Following independent studies, using JQ1 to target BRD4 and SEs, have demonstrated similar effects in a broad spectrum of cancer types, such as colorectal cancer, ovarian cancer, Merkel cell carcinoma, B cell lymphoma, and alveolar rhabdomyosarcoma." (PMID 31724731, 2019). "Studies in cancer have found that NF-κB is regulated by BRD4, acting as a coactivator, by binding to acetylated lysine-310 residue of the RelA NF-κB subunit." (PMID 31780938, 2019). "JQ1 is a thieno-triazolo-1,4-diazepine that binds selectively to the acetyl lysine pocket of the BRD module and was shown to inhibit cancer cell proliferation in several tumor models, including the BRD4-NUT carcinoma, generally by inhibiting Myc signaling." (PMID 31226848, 2019). "In accordance with experimental data from other cancers, our data showed that BRD4 inhibition leads to variable apoptosis induction." (PMID 30761268, 2019). "Many oncogenes regulating cancer cell proliferation, resistance to apoptosis, and aggressiveness are under the control of BRD4." (PMID 30841549, 2019). "The BET bromodomain protein BRD4 is a chromatin reader that regulates transcription, including in cancer." (PMID 30846826, 2019).
cancer (continued). "Strikingly, HAT1 was involved in the cancer immunity response by regulating the PD-L1 expression, and this process was mainly mediated by BRD4." (PMID 30709380, 2019). "These inhibitors have gone into clinical trials for multiple cancer indications, and one Brd4 inhibitor has received fast-track designation from the FDA for myelofibrosis." (PMID 31292434, 2019). "The cluster has also been shown to be regulated by bromodomain protein 4 (BRD4) which is increased in MYC-driven cancers." (PMID 31581940, 2019). "The expression of BRD4 in tissues of patients with various types of cancer was investigated in data from The Cancer Genome Atlas (TCGA)." (PMID 30988278, 2019). "BRD4 was firstly described as a proliferative target in a cancer study of nuclear testis protein (NUT) midline carcinoma caused by the nuclear translocation of the BRD4-NUT oncogene product." (PMID 31780938, 2019). "In the nucleus, YAP-TAZ-TEAD1 complexes interact with BRD4 and drive the expression of sets of genes involved in cancer transcriptional programs." (PMID 31817001, 2019). "Alteration of m6A levels participates in cancer pathogenesis and development via regulating expression of tumor-related genes like BRD4, MYC, SOCS2 and EGFR." (PMID 31801551, 2019). "BRD4, a major BET protein, has also been implicated as a modulator of YAP/TAZ transcriptional activity at distinct promoters in cancer cells." (PMID 31849712, 2019). "We describe the first report of a molecular characterized BRD4-NUT carcinoma in Brazil and Latin America." (PMID 31492174, 2019). "Targeting the BRD4/acetylated RELA axis should be of value in NFκB-dependent cancers, such as lymphoma, where aberrant NFκB signaling is frequent, including through genetic mechanisms." (PMID 29415456, 2018). "The bromodomain containing protein 4 (BRD4) recognizes acetylated histone proteins and plays numerous roles in the progression of a wide range of cancers, due to which it is under intense investigation as a novel anti-cancer drug target." (PMID 29941841, 2018). "Overexpressed BRD4 is found in a variety of cancers and has been shown to be an adverse predictor for survival in some cancers." (PMID 29434197, 2018). "A new small molecular inhibitor, JQ1, targeting BRD4, which recognizes the acetylated lysine residues, has been shown to induce cell cycle arrest in different cancers by inhibiting MYC oncogene." (PMID 29996811, 2018). "Numerous studies have shown BRD4 to be important in the promotion of NF-kB-mediated transcription of inflammatory genes, whose functions in cancer initiation and progression have shown to be manifold and complex." (PMID 30029633, 2018). "While anti-cancer and anti-inflammatory properties led to the approval of several inhibitors of BRD4 for drug therapy, their toxicological properties have been poorly investigated." (PMID 30333915, 2018). "The CDK7 inhibitor THZ1 and BRD4 inhibitor JQ1 can efficiently target MYC driven transcriptional amplification in other types of cancers, here we studied the potential role of THZ1 and JQ1 in regulation of ostesosarcoma." (PMID 29644114, 2018). "BRD4 assembles transcriptional machinery at gene super-enhancer regions and governs the expression of genes that are critical for cancer progression." (PMID 30518851, 2018). "Prominent examples are the HMT DOT1L that regulates HOX gene expression and the bromodomain-containing protein BRD4, which regulates the expression of super-enhancer linked genes in AML and other cancers." (PMID 29527516, 2018). "As well, ChIP seq data showed that BRD4 occupies many ENHs and promoters also in non-cancer cells and generally contributes to gene expression." (PMID 30466442, 2018).
cancer (continued). "Recently, independent reports highlighted a possible role of BRD4 in aberrant telomere regulation in cancer, even if the mechanisms through which BRD4 cooperates to telomere elongation is still poorly defined." (PMID 30466442, 2018). "The BRD4 protein plays various roles in the progression of different types of cancers, which makes it an attractive drug target." (PMID 29941841, 2018). "Inhibition of BRD4 shortcuts the communication between SEs and target promoters with a subsequent cell-specific repression of oncogenes to which cancer cells are addicted and cell death." (PMID 30466442, 2018). "Since BRD4 is considered the most important target of the BET inhibitor JQ1 in various cancers, we evaluated BRD4 protein expression in a series of UCCs compared to the benign urothelial control cell lines HBLAK, TERT-NHUC, and NHUC." (PMID 29312470, 2018). "BRD4 is a transcriptional and epigenetic regulator that plays a pivotal role during embryogenesis and cancer development." (PMID 30466442, 2018). "It is noteworthy that the inhibition of BRD4 can exert an additional anti-cancer mechanism besides the inhibition of general transcriptional machinery in ATL or HTLV-1-infected cells." (PMID 29724031, 2018). "Our results reveal a novel mechanism by which BRD4 regulates cancer cell proliferation by modulating the cellular senescence through E2F/miR-106b-5p/p21 axis and provide new insights into using BET inhibitors as potential anticancer drugs." (PMID 29434197, 2018). "BRD4 (Bromodomain-Containing Protein 4) is a transcriptional epigenetic regulator that plays a crucial role in cancer and inflammatory diseases." (PMID 30029633, 2018). "We utilized The Cancer Genome Atlas (TCGA) data to interrogate BRD4 amplification across all represented cancer subtypes." (PMID 30036377, 2018). "BRD4 is involved in the development of hematological malignancies and solid tumors, emerging as a promising therapeutic target for cancer treatment." (PMID 29434197, 2018). "It seems therefore that impairment of kinase signaling aggravated anti-BRD4 mediated apoptosis in these cancer cell lines." (PMID 29899872, 2018). "In clinical studies, BET inhibitors have been shown to suppress inflammation in various cancers, suggesting a potential link between BRD4 and immune infiltration in cancer." (PMID 30029633, 2018). "Here, we aimed to elucidate the anti-cancer effects of JQ1 and the mechanisms underlying BRD4 inhibition in sunitinib-sensitive and -resistant ccRCCs." (PMID 29796168, 2018). "Using an unbiased screening based on a lentiviral shRNAs library targeting 706 known kinases and relative genes, BRD4 has been identified as necessary for telomere maintenance in cancer cells." (PMID 30466442, 2018). "The present review provides a brief overview of the structure and function of BET family proteins and then examines the connections between NFκB and BRD4 signaling, using the inflammatory response and cancer cell signaling as study models." (PMID 29415456, 2018). "In the present work, we attempt to discuss the most recent evidence of a transversal function of BRD4 in keeping genome stability providing new insights into the cytotoxic effects of BETi in cancer cells." (PMID 30466442, 2018). "In a variety of human AML cell lines, suppression of BRD4 was shown to suppress MYC effectively suggesting a potential target for cancer treatment." (PMID 29527516, 2018). "The functional involvement of BRD4 in DNA damage checkpoint activation and DNA repair holds relevant implications for cancer therapy and envisages new settings for the employment of BETi both alone or in combination." (PMID 30466442, 2018). "Our data demonstrates that ponatinib significantly increases the sensitivity of carcinoma cells to BRD4 targeted drugs." (PMID 29899872, 2018). "Our results suggest that Brd4 mediates most of the anti-cancer effects of JQ1 and that the major function of Brd4 in this process is the recruitment of P-TEFb." (PMID 28490802, 2017).
cancer (continued). "BRD4 inhibition suppresses growth and metastasis of several malignant tumors and BRD4 has been validated as a therapeutic target for tumor treatment." (PMID 28545522, 2017). "Recognition of the importance of BRD4 in cancer has led to the development of a new generation of anti-cancer compounds that specifically target the BET (bromodomain and extra-terminal motif) family of proteins, of which BRD3 and BRD4 are key members." (PMID 29348827, 2017). "Brd4 is a prominent drug target for cancers but its role in normal cell differentiation and tissue development is largely unexplored." (PMID 29263365, 2017). "As literature reports, disrupting the protein-protein interactions between BRD4 and acetyl-lysine can effectively block cell proliferation in cancer, cytokine production in acute inflammation, as well as alleviate HIV-1 latency." (PMID 28300771, 2017). "BRD4 has been reported as target in various cancer types as ovarian, breast, gastric, andregulation of transcriptions factor MYC." (PMID 29077030, 2017). "Suppression of BRD4 expression using short hairpin RNAs or small-molecule inhibitors has shown anti-cancer effects." (PMID 28415703, 2017). "BRD4 tag density distribution on DHS sites of this subgroup of FoxO-regulated genes revealed an increased BRD4 occupancy during cancer cachexia, which was abrogated by (+)-JQ1 treatment." (PMID 29167426, 2017). "Currently, more than a dozen of BRD4 inhibitors have progressed into human clinical trials for the treatment of cancer or other diseases." (PMID 28300771, 2017). "The BRD4 protein plays several roles in cancer by upregulating oncogenes, such as c-myc, and genes related to proliferation, apoptosis suppression, and inflammation." (PMID 29186801, 2017). "The case of BRD4 is remarkable in that it appears to affect the maintenance of a wide range of cancers." (PMID 28718414, 2017). "Particularly, BRD4 can regulate cell growth that leads to the development and progression of many diseases including cancer." (PMID 28415703, 2017). "Specifically, bromodomain protein Brd4 is a ‘reader’ protein that is currently evaluated as a potential drug target in cancer therapy." (PMID 28490802, 2017). "Combinatorial therapies using MEK inhibitors or BRD4 inhibitors together with NSD2 inhibition are likely to be effective in fighting RAS-dependent cancers with NSD2 overexpression." (PMID 27604143, 2016). "Because of its fundamental role in transcriptional regulation, Brd4 has also been investigated as a therapeutic target to combat a number of cancers with deregulated Brd4 activity." (PMID 26727473, 2016). "Very recent results demonstrated that inhibiting the epigenetic reader BRD4 has notable efficacy in diverse cancer types." (PMID 27081696, 2016). "Recent studies have recognized the important role of the BET family member BRD4 at super enhancer regions involved in the regulation of specific oncogenes in different cancers, including MM, and highlighted the feasibility of blocking its function using BETi." (PMID 27903272, 2016). "Multivariate analysis revealed that BRD4 expression level in cancer tissues was an independent prognosticator for OS." (PMID 26840017, 2016). "Although BRD4 has been regarded as a potential therapeutic target for many diseases including some cancers, it remains elusive in NSCLC." (PMID 26840017, 2016). "This selectivity window translated in a more BRD4-specific downstream transcriptional response in cancer cells treated with MZ1 as compared with treatment with (+)-JQ1." (PMID 27193077, 2016). "We focused on the ED group, which more likely has direct targets of BRD4 inhibition; the group was greatly enriched in cancer related categories." (PMID 27081696, 2016). "We demonstrate that one BRD4 inhibitor is effective in suppressing cancer growth and preventing distal metastasis through multiple means." (PMID 25603177, 2015). "Inhibitors of Brd4 slows tumor cell growth by blocking SE-mediated activation of cancer driver genes." (PMID 26546038, 2015).